IL1B (interleukin 1 beta)
Diseases named in the same sentence as IL1B in open-access papers (continued):
Sharing a sentence is not in itself a finding about the gene and the disease.
Cognitive impairment (continued). "As a potent activator for exacerbating neuroinflammation, IL-1β has been reported to suppress BDNF-dependent synaptic efficacy, resulting in cognitive impairment." (PMID 28265338, 2017). "Treatment with an IL-1β neutralizing antibody alleviated TBI-induced microglial activation, neutrophil infiltration, cerebral edema, and cognitive deficits in mouse models of TBI." (PMID 28086980, 2017). "β-Asarone improved cognitive impairment, alleviated Aβ deposition and hippocampal damage, and inhibited GFAP, AQP4, IL-1β, and TNF-α expression." (PMID 29599803, 2017). "Given that recent studies have suggested that isoflurane may induce neuroinflammation which may be associated with cognitive impairment, we examined with Western blot assays the effects of isoflurane and propofol on the proinflammatory cytokines, TNF-α, IL-1β and IL-6, in the cortex at P7." (PMID 24932894, 2014). "Although the role of microglial priming remains unproven, activated microglia robustly expressed COX-1 and the described cognitive deficits were dependent on both COX-1-mediated prostaglandins and IL-1β." (PMID 24067500, 2013). "Also, isoflurane did not induce cognitive impairment in the IL-1β deficient mice." (PMID 23915963, 2013). "In a model of peripheral surgery-induced cognitive impairment, the memory dysfunction elicited following tibial fracture was shown to be both TNF-α and IL-1β-dependent." (PMID 23840908, 2013). "Weak to moderate correlations were observed between IL-1β, IL-6, TNF-α levels, and different degrees of cognitive impairment." (PMID 24339912, 2013). "Our study aligns with prior research, demonstrating that aerobic exercise suppresses the activation of M1 phenotype microglia in the hippocampus of mice with AS-induced cognitive impairment and reduces the expression of inflammatory cytokines IL-6, TNF-α, and IL-1β." (PMID 40556958, 2025). "Our key findings demonstrated that both rifaximin and lactulose significantly decreased serum and cerebrospinal fluid ammonia levels, improved cognitive deficits in MHE rats, and reduced systemic inflammation, specifically by lowering portal LPS levels and serum TNF-α and IL-1β." (PMID 40526631, 2025). "In this study, we demonstrated that prolonged systemic exposure to IL‐1β significantly impairs cognitive flexibility in the BMT, with a notable portion of subjects showing resilience to this inflammation‐induced cognitive deficit during the reversal test phase of the BMT." (PMID 39996443, 2025). "Andrographolide (10 mg/kg, ip, 4 weeks) improved CCH-induced cognitive deficits and hippocampal apoptosis, inhibited astrocyte activation and decreased the expression of TNF-α, IL-1β caspase-3 in the hippocampus, while alleviated 2VO-induced decreases in the expression of BDNF and TrkB." (PMID 41230091, 2025). "Serum levels of BDNF, BACE1, VEGF, GFAP, and IL-1β were evaluated through ELISA in patients with and without cognitive impairments." (PMID 40291844, 2025). "Increased NLRP3 activation and IL-1β expression have been detected in the hippocampus and amygdala of HFD-fed mice, which may contribute significantly to cognitive impairment." (PMID 41194915, 2025). "We noticed that cytokines IL-1β, TNF-α and IL-6 changes were rapid but transient, while C3 upregulation was delayed but prolonged, a pattern that concur more with the time course of cognitive deficits." (PMID 38427092, 2024). "In addition, sleep deprivation significantly elevated the levels of proinflammatory cytokines including IL‐1β, IL‐6, and TNF‐α in the hippocampus and resulted in cognitive impairment during the novel object recognition test." (PMID 38688894, 2024). "Previous reports found a negative correlation between IL1β levels and cognitive impairment levels, indicating that activated microglia and complement systems, along with increased formation of cytokines and chemokines, were involved in AD progression." (PMID 39109268, 2024).
Cognitive impairment (continued). "This may be associated with hippocampal structural damage and elevated levels of IL-1β, IL-6, and TNF-α in the hippocampus, which leads to blood–brain barrier rupture and cognitive impairment." (PMID 40017811, 2024). "The levels of inflammatory cytokines (interleukin-1 beta (IL-1β), interleukin-6 (IL-6), interleukin-8 (IL-8), and tumour necrosis factor-alpha (TNF-α)) were measured using an assay method and compared with the subjective cognitive impairment." (PMID 39484178, 2023). "However, in support of our observations, heightened levels of IL-1β and TNF-α have been found within mdx murine brains, who also displayed cognitive impairment similar to those in DMD patients." (PMID 37108685, 2023). "Fisetin attenuated histological injury, MDA levels, inflammasome pathway activation, and the mediated production of cytokines IL-1β and IL-18, apoptosis, as well as increased BDNF expression, and reduced astrocyte, microglial activation, and cognitive deficits following VaD." (PMID 35740470, 2022). "Adult mice injected perinatally with IL-1β also exhibited cognitive deficits in the novel object recognition task, but no defects in exploratory behavior by P30." (PMID 35368298, 2022). "In conclusion, Yisui multipurpose soup could effectively protect D-galactose-induced neuronal cell cognitive impairment by orchestrating expressions of the inflammatory factors TNF-α, iNOS, NO, and IL-1β and the apoptosis-related proteins Bcl-2 and Bax." (PMID 35754679, 2022). "We found that IL-1β infusion into the CA1 region induced significant cognitive impairment, as measured by the NOR test, similar to that in CIA mice, indicating that IL-1β is sufficient to induce cognitive impairment." (PMID 35982301, 2022). "Another experimental study reported that in Aβ42-induced rats, β-asarone improved cognitive impairment and alleviated Aβ deposition by protecting astrocytes, which was possibly achieved by reducing the levels of TNF-α and IL-1β and then downregulating AQP4 expression." (PMID 35215287, 2022). "Pretreatment with dexmedetomidine alleviated intestinal injury and decreased the serum and hippocampal levels of NE, IL-1β, TNF-α, and MDA at 24 h after intestinal ischemia reperfusion, decreased TH-positive neurons in the locus coeruleus, and ameliorated cognitive impairment." (PMID 35945306, 2022). "Moreover, miR-485-3p ASO treatment reduced secretion of proinflammatory cytokines, including IL-1β and TNF-α, and eventually relieved cognitive impairment." (PMID 34884940, 2021). "Notably, it has been demonstrated that onjisaponin B can prevent cognitive impairment in d-gal induced aging in rats by regulating inflammatory mediators (TNF-α, IL-6, and IL-1β) and oxidative stress-related indicators (MDA, SOD, GSH, and GSH-PX)." (PMID 33878733, 2021). "Further, HIV gp120 can upregulate FHC in neuronal/glial cocultures via an IL-1β dependent mechanism, suggesting opioid use and HIV infection may act through overlapping or shared mechanisms to induce cognitive impairment." (PMID 34429135, 2021). "In an animal study, Sun and his colleagues found that Rehmannioside A could attenuate cognitive deficits in rats with VD through reducing the release of proinflammatory cytokines, including TNF-α, IL-1β, and IL-6." (PMID 32617097, 2020). "It is well established that inflammatory responses, including activation of glial cells and production of inflammatory cytokines such as IL-1β, IL-6, COX-2, iNOS, and TNF-α, induced by CCH could further result in neuronal cell death and cognitive deficits." (PMID 31900229, 2020). "Proinflammatory cytokines IL-1β, IL-6, and TNF-α independently resulted in cognitive impairment." (PMID 32063834, 2020). "Thus, pretreatment with Tan IIA significantly prevented cognitive impairment induced by CCL2 and inhibited the expression of IL-1β and IL-6." (PMID 32185196, 2020).
Cognitive impairment (continued). "The synthesis and release of proinflammatory cytokines such as IL-1β, IL-6, and TNF-α contribute to cognitive impairment by affecting cognitive processes such as synaptic plasticity, neurogenesis, neuromodulation, memory consolidation, and long-term potentiation (LTP)." (PMID 31565046, 2019). "Activated glia stimulated by Aβ has been reported to upregulate the expression of several proinflammatory chemokines and cytokines including IL-1β, IL-6, and TNF-α, which could result in an increase of Aβ production, neuronal death, and cognitive deficits." (PMID 30871577, 2019). "Here, we show for the first time that therapeutically targeting IL-1RI may be more likely to provide effective treatment for patients suffering cognitive deficits after TBI than drugs that specifically target individual IL-1α and IL-1β signaling." (PMID 29662944, 2018). "It has been shown that activation of IL-1β signaling triggers the activation of kinases CDK5, GSK3β, and p38 mitogen-activated protein kinase (p38-MAPK), resulting in tau hyperphosphorylation and cognitive impairment in the 3xTg-AD mouse model." (PMID 30249283, 2018). "We found that isoflurane GA caused upregulations of hippocampal NLRP3, cleaved caspase-1, interleukin-1β (IL-1β), and IL-18 and the activation of pyroptosis, which is NLRP3 inflammasome-dependent; this consequently gave rise to neuronal damage and cognitive impairment in aged mice." (PMID 30524241, 2018). "In addition, HBO2T reversed the HAE-induced upregulation of brain levels of proinflammatory cytokines including IL-1β, IL-6, TNF-α, and IF-γ as well as cognitive deficits." (PMID 30515398, 2018). "Previous studies also showed that HHcy may result in neuroinflammation as indicated by elevated levels of IL1β, TNFα and IL6 in mice brain tissue, and these inflammatory mediators were all shown to independently result in cognitive impairments." (PMID 30425189, 2018). "This study was aimed to explore whether hypercapnia would partake in increasing IL-1β secretion via activating the NLRP3 (NLR family, pyrin domain-containing 3) inflammasome in the hypoxic CNS and in aggravating cognitive impairment." (PMID 29304864, 2018). "To determine whether the inflammatory cytokines was involved in the cognitive impairment of the diabetic rats, we examined TNF-α, IL-1β and IL-6 mRNA expression in the brain." (PMID 29867440, 2018). "Additionally, heat stress can cause glial activation with NF-κB pathway in the hippocampus, which subsequently led to the upregulation of TNF-α, IL-1β, iNOS and COX-2, resulting in neurodegeneration and cognitive impairment." (PMID 28946610, 2017). "Furthermore, NF-κB is also reported to execute the generation of proinflammatory cytokines such as IL-1β and TNF-α, which ultimately exacerbates neurotoxicity and cognitive deficits." (PMID 26881113, 2016). "Taken together, our data suggest that heat stress might induce activation of NF-kB, which subsequently leads to the elevation of TNF-α and IL-1β, and the up-regulation of iNOS and COX-2, resulting in cognitive deficits in mice." (PMID 26001832, 2015). "Similarly, high mobility group box-1, interleukin (IL)-1β and NADPH oxidase have been shown to have roles in long-term cognitive impairment induced in the cecal ligation and puncture model of polymicrobial sepsis." (PMID 25802557, 2015). "Moreover, we measured proinflammatory cytokines IL-1β, IL-6 and TNF-a concentration at a time when animals had significant cognitive impairments." (PMID 23613842, 2013). "Hypercapnia-induced IL-1β overproduction via activating the NLRP3 inflammasome by hypoxia-activated microglia may augment neuroinflammation, increase neuronal cell death, and contribute to the pathogenesis of cognitive impairments." (PMID 39347154, 2024).
Cognitive impairment (continued). "Our results demonstrated that T3 treatment reversed cognitive impairment and increased Akt and GSK3 phosphorylation in the treated group, while also reducing microglial activation (Iba-1) and GFAP expression (reactive astrocytes), along with TNF-α, IL-6, and IL-1β levels in the hippocampus." (PMID 39513900, 2024). "One possibility might be that neuronal IL-1β is responsible for the post-injury cognitive deficits, and nVNS administered post-CHI did not reduce neuronal IL-1β beta activation, rendering nVNS ineffective." (PMID 38435077, 2024). "Therefore, our findings suggest that the NLRP3 inflammasome may be a new therapeutic target for cognitive impairment, and that targeting the NLRP3/Caspase-1/IL-1β signaling axis is a promising approach for the treatment of postoperative inflammation." (PMID 36934348, 2023). "It has been reported that the inflammasome activation and downstream IL-1β processing were found at 14 months post repetitive mild TBI and IL-1 receptor 1 knockout attenuated accumulation of pro-IL-1β and misfolded tau, thus protected against cognitive deficits post TBI." (PMID 35669106, 2022). "However, AST treatment remarkably lowered the IL-1β expression and enhanced IL-4 expression in the hippocampus and prefrontal cortex, indicating that the alleviation of AST in cognitive impairment may correlated with suppression of inflammatory response." (PMID 33208152, 2020). "Repeated intraperitoneal injection of LPS derived from Porphyromonas gingivalis induced cognitive deficits, intraneuronal Aβ accumulation, microglial activation, and increases in IL-1β in middle-aged (12 months) wild-type C57BL/6 mice but not in young (2 months) mice." (PMID 32391019, 2020). "Several biomarkers were also highlighted as potential biomarkers of GDM-related cognitive impairment such as AGEs, serine-phosphorylated IRS-1 and inflammatory markers such as tumor necrosis factor α (TNF-α), high-sensitivity C-reactive protein (hs-CRP), leptin, interleukin 1β (IL-1β), and IL-6." (PMID 30563117, 2018). "Likewise, pre-treatment with the IL-1β antagonist IL-1ra reversed the impaired neurogenesis elicited by in vitro IL-1β or by stressors as well as the down-regulated hippocampal BDNF and cognitive impairments elicited by social isolation in mice." (PMID 23675319, 2013). "Although previous studies showed that IL-1β can regulate the expression of KCC2 in the CNS, it is unknown whether abnormal GABAergic shift induced by altered expression of KCC2 is involved in neonatal sepsis- or severe inflammation-induced long-term cognitive impairment." (PMID 35883093, 2022). "Herein, we hypothesized that sustained elevation of IL-1β levels affected the GABAergic shift by modulating KCC2 expression in CA1 hippocampal pyramidal neurons during the development period, which finally contributed to long-term cognitive impairment after neonatal severe inflammation." (PMID 35883093, 2022). "Although there was no additive effect seen on cognitive flexibility or in IL-1β in the prefrontal cortex, the authors suggest that IL-1β may be involved in crosstalk between hippocampal and cortical-related cognitive impairments seen after an early age mild TBI." (PMID 34484104, 2021). "Furthermore, inhibition of sEH reduces cognitive impairment in AD mouse models by reducing OS, endoplasmic reticulum (ER) stress and, most importantly, by reducing mediators of neuroinflammation, such as tumor necrosis factor (TNF-α) and interleukin 1 beta (IL-1β)." (PMID 33810307, 2021). "The present results suggest that hypercapnia-induced IL-1β overproduction via activating the NLRP3 inflammasome by hypoxia-activated microglia may augment neuroinflammation, increase neuronal cell death, and contribute to the pathogenesis of cognitive impairments." (PMID 29304864, 2018).
Cognitive impairment (continued). "Therefore, the diminished IL-10, in combination with increased IL-1β, that we observed in DEP/NR males could affect their relative vulnerability to cognitive impairments and mood dysregulation, compared with DEP/​NR females, which did not exhibit such a proinflammatory bias." (PMID 23823752, 2013). "Recombinant CXCL13 induced cognitive deficits and increased the expression of phospho-ERK as well as IL-1β and TNF-α in hippocampus of wild-type mice, but not CXCR5−/− mice." (PMID 33161894, 2020). "In parallel with the amelioration of the cognitive impairment, diabetic brain MDA levels and the mRNA levels of gp91phox, p22phox, and IL-1β were significantly decreased, to non-diabetic control levels." (PMID 29453337, 2018). "This supposition is supported by one study of non-CNS cancer patients demonstrating cognitive impairment that was correlated with pro-inflammatory plasma biomarkers including interferon-gamma (INF-Υ), interleukin one beta (IL-1β), interleukin two (IL-2) and fibroblast growth factor two (FGF2)." (PMID 38715789, 2024).